IDH1 (isocitrate dehydrogenase (NADP(+)) 1)
Diseases named in the same sentence as IDH1 in open-access papers (continued):
Sharing a sentence is not in itself a finding about the gene and the disease.
leukemia (continued). "Despite the limitation of our sample size, this study has critically highlighted the prevalence of IDH1 and IDH2 in leukemia patients in the Saudi population." (PMID 34946913, 2021). "Despite parallel mechanisms of transformation, IDH1+ and IDH2+ leukemias show differences in both in vitro and clinical studies." (PMID 33976256, 2021). "In a mouse model of leukemia, HMS-101 blocked the production of 2-HG and inhibited proliferation of IDH1-mut cells." (PMID 30857299, 2019). "Yet, we found that EZH2 was capable of generating leukemia in mice even in the absence of IDH1 or NRAS." (PMID 40362463, 2025). "This includes leukaemia, where Aza, BET and IDH1/2 inhibitors have been used in clinical trials." (PMID 37614712, 2023). "We observed that IDH1/2 VAF in morphologic leukemia free state was not reduced below 2.5% in 15 out of 62 cases (24%, 10 IDH2 R140Q, 3 IDH2 R172K, 1 IDH1 R132H and 1 IDH1 R132C)." (PMID 34153064, 2021). "The risk of leukemic transformation is context dependent—in PMF, the presence of IDH-1 or -2 increases risk by three- to six-fold; in PV, the risk is up to 55-fold higher, while in ET, IDH mutation status was not contributory to leukemia free survival." (PMID 32640569, 2020). "NPM1 is usually a secondary or downstream mutation, whereas mutations in DNMT3A, ASXL1, IDH1/2, and TET2 occur very early during clonal evolution but are typically not sufficient to cause leukemia on their own." (PMID 28197208, 2017). "Interestingly in IDH IDH1/2-mutant AML, leukemia cells can tolerate this inhibitory activity." (PMID 34571995, 2021). "Furthermore, IDH1+ and IDH2+ leukemias differ in their mutational profiles, with high incidence of DNA (cytosine-5)-methyltransferase 3A (DNMT3A) mutations reported in IDH1+, but not IDH2-R140+ AML38,43." (PMID 33976256, 2021).
anaplastic astrocytoma (77 papers, 2012 to 2025). "In contrast, diffuse astrocytoma and anaplastic astrocytoma are positive for IDH1 mutations and show loss of ATRX nuclear staining." (PMID 39295729, 2024). "By excluding IDH1 mutated-patients, both Anaplastic Astrocytomas (AAs) and GBMs display significant reduction in 5mC compared to normal brain tissues." (PMID 35501312, 2022). "In a majority of cases, the IDH1 R132H mutation is unique to the tumor, although rare cases of anaplastic astrocytoma have been described in patients with mosaic IDH1 mutations (Ollier disease or Maffucci syndrome)." (PMID 32010615, 2020). "One (GBM07) tested positive for the IDH1 R132H mutation, proving evolution from a previously diagnosed anaplastic astrocytoma." (PMID 32899203, 2020). "A study conducted on 18 grade III anaplastic astrocytomas has shown that the presence of the IDH1-R132H mutation was associated with the up-regulation of a truncated C-terminal form of Alpha-crystallin B chain protein (CRYAB)." (PMID 31357616, 2019). "IDH1 mutational status was assessed in 60 samples (five pilocytic astrocytomas, nine diffuse astrocytomas, seven anaplastic astrocytomas, and 39 GBMs), and we observed that 17/60 (28.3%) of cases presented IDH1 mutation." (PMID 27172220, 2016). "Final pathological review of the specimen demonstrated an IDH1 (R132H)-mutated WHO III anaplastic astrocytoma." (PMID 26911558, 2016). "In fact, we found 77.8% (7/9) of diffuse and 100% (7/7) of anaplastic astrocytomas presenting IDH1 mutation, whereas 92.9% (3/42) of GBMs were wild-type for IDH1 mutation, corroborating this data." (PMID 27172220, 2016). "A second surgery was performed, and pathology demonstrated recurrent tumor, consistent with IDH1-mutated anaplastic astrocytoma." (PMID 26911558, 2016). "In this report, we describe a patient who underwent surgical resection of a right temporal lobe WHO III IDH1-mutated anaplastic astrocytoma, followed by adjuvant radiation and temozolomide." (PMID 26911558, 2016). "We describe a patient who underwent surgical resection, followed by adjuvant radiation and temozolomide of a World Health Organization (WHO) III anaplastic astrocytoma in the right temporal lobe, exhibiting an IDH1 (R132H) mutation." (PMID 26911558, 2016). "Somatic mutations in isocitrate dehydrogenase 1 and 2 (IDH1/2) were detected in approximately 80 % of diffuse and anaplastic astrocytomas as well as secondary GBMs." (PMID 24810474, 2014). "Heterozygous IDH1 R132H mutations are common in adolescent and young adult anaplastic astrocytomas." (PMID 32010615, 2020). "Generally, the vast majority of histologically diagnosed diffuse and anaplastic astrocytomas has a characteristic mutation of the isocitrate dehydrogenase 1/2 gene (IDH1/2), whereas glioblastomas are further distinguished into two genetic subgroups based on the mutational status of IDH." (PMID 32604718, 2020). "Subsequently, the patient underwent subtotal resection of the temporal lesion with final pathology demonstrating a WHO III anaplastic astrocytoma with intact 1p/19q chromosomal arms and positive for the IDH1 (R132H) mutation, based on immunohistochemical staining." (PMID 26911558, 2016). "A series of 193 patients with astrocytic neoplasms (111 diffuse and 82 anaplastic astrocytomas), grouped according to prelabeled anatomical structures and the risk of surgery, were retrospectively reviewed for IDH1 and IDH2 mutations to compare the tumor location and MRI features." (PMID 24932255, 2014). "In addition, the two cases that progressed to anaplastic astrocytomas also displayed IDH1 mutations." (PMID 23826216, 2013).
anaplastic astrocytoma (continued). "Fifty-one patients had IDH1/2-mutant tumors that were transformed from WHO Grade III anaplastic astrocytoma or low-grade gliomas, or diagnosed as IDH-mutant GBM by 2016 WHO criteria." (PMID 39554793, 2024). "A study in Japan showed that IDH1 mutation was found in 10% of GBM (Grade IV), 28% of anaplastic astrocytoma (grade III), and 59% of diffuse astrocytoma (grade II)." (PMID 32856857, 2020). "Patient 07's IDH1‐mutant GBM tumor had progressed from an initial grade III anaplastic astrocytoma, thus representing a secondary GBM." (PMID 32578964, 2020). "Using the C-circle assay, which requires only 30 ng of tumor DNA, we have shown that ALT intensity correlates with patient age in IDH1/2-, ATRX-mutated anaplastic astrocytomas (AA)." (PMID 31706351, 2019). "Patients with WHO grade III anaplastic astrocytoma and GBM carrying IDH1 mutations have a significantly longer median overall survival than patients with wild-type IDH1." (PMID 30388142, 2018). "For example, in one patient with anaplastic astrocytoma IDH1 wild-type (patient #37), the extracted TAC was centroid #2 when considering a ROI on the whole tumor." (PMID 29953478, 2018). "Patient 4 was a 57 year-old man whose original tumor was an IDH1/2 wild type anaplastic astrocytoma with unmethylated MGMT promoter and PTEN deletion." (PMID 29113409, 2017). "In one of these studies, 5-azacytidine was administered intraperitoneally to nude mice bearing subcutaneous xenografts derived from an IDH1-mutant anaplastic astrocytoma specimen." (PMID 27556016, 2016). "She underwent a stereotactic biopsy confirming an anaplastic astrocytoma, IDH1 wild-type, and MGMT unmethlyated." (PMID 27809808, 2016). "One large retrospective study demonstrated that IDH1 wild-type anaplastic astrocytomas had inferior survival outcomes to IDH1 mutant GBs." (PMID 26646075, 2015). "Overall, JHH-273 reflects the hypermethylated genomic landscape of the original patient tumor and characteristic of an IDH1 (R132H) anaplastic astrocytoma." (PMID 24077805, 2013). "Here we report the generation of an endogenous IDH1 anaplastic astrocytoma model which rapidly grows in vivo, produces 2-HG and exhibits DNA hypermethylation." (PMID 24077805, 2013). "The high levels of CpG methylation were consistent with other primary patient IDH1 (R132H) anaplastic astrocytoma samples." (PMID 24077805, 2013). "Here we report the generation of an endogenous IDH1 anaplastic astrocytoma and the preclinical demonstration of efficacy and mechanism of 5-azacytidine in this model." (PMID 24077805, 2013). "Anaplastic astrocytomas with IDH1/2 wild type are generally treated like glioblastomas." (PMID 33836671, 2021). "Pathology was compatible with a grade 3 IDH1-mutant anaplastic astrocytoma." (PMID 34026631, 2021). "Interestingly, we observed an inverse correlation between patient age and ALT intensity in IDH1/2-, ATRX-mutated anaplastic astrocytomas, ALT intensity being significantly higher in younger patients." (PMID 31706351, 2019). "A second biopsy was performed, confirming an anaplastic astrocytoma, IDH1 wild-type." (PMID 27809808, 2016). "With anaplastic astrocytomas, patients harboring IDH1 mutation had an overall survival of 65 months compared to 20 months for patients without IDH1 mutation." (PMID 26858939, 2016). "IDH1-R132H/C mutations were found in 7 out of 8 WHO II grade tumours (88%, R132H in six samples and R132C in one sample), 1 out of the 2 anaplastic astrocytomas (50%, R132C), and as expected by the low frequencies reported in literature in none of the GBMs (0%)." (PMID 25279461, 2014).
anaplastic astrocytoma (continued). "In 2009, Yan's study indicated that mutations of IDH1 and IDH2 occurred in majority of several types of malignant gliomas and reported the incidence of IDH1/2 mutation in diffuse astrocytoma (90%), anaplastic astrocytoma (73%) primary GBM (5%) and secondary GBM (85%)." (PMID 24810474, 2014). "Hence, anaplastic astrocytoma with IDH1 wild-type and MGMT methylation patients may be more suitable treated with chemotherapy and if the MGMT is unmethylated, they are better treated by radiotherapy only." (PMID 33671796, 2021). "Delaying treatment to wait for the molecular analysis (for instance IDH1-2 mutations results) could be detrimental for the patient, especially when the prognostic role of IDH1-2 status in HGG is debated, as described in recent studies which propose CDKN2A/B for anaplastic astrocytoma." (PMID 33798233, 2021). "Another patient had re-resection of a recurrent, non-hypermutated IDH1-mutant anaplastic astrocytoma, which recurred again as a hypermutated GBM on the subsequent re-resection." (PMID 32051040, 2020). "Our chondrosarcoma cell line panel contained one homozygous mutant IDH2 cell line (L2975) that, contradictory to what has been shown in the anaplastic astrocytoma WHO grade III cell line IMA, revealed elevated levels of D-2-HG comparable to heterozygous mutant IDH1/2 cell lines." (PMID 25895133, 2015). "33-year-old nulligravid woman with newly diagnosed anaplastic astrocytoma (AA; WHO grade III, IDH1-negative) sought fertility preservation." (PMID 29739361, 2018).
diffuse astrocytoma (72 papers, 2009 to 2025). A low-grade (WHO grade II) astrocytic neoplasm. "Among patients previously diagnosed as IDH-mutant GBM, anaplastic astrocytoma, or diffuse astrocytoma, 60 cases exhibited IDH1 or IDH2 mutations and were reclassified as A-IDHm." (PMID 38893152, 2024). "The frequency of IDH1-positive diffuse astrocytomas was 33 (64.7%), and loss of ATRX was seen in 12 (23.5%) cases." (PMID 39192927, 2024). "The most common mutations in diffuse astrocytomas are missense mutations in IDH1, which account for over 70% of cases, with a substitution of histidine for arginine at codon 132 (IDH1 R132H) being the most frequent alteration." (PMID 37239289, 2023). "These IDH1-mutated samples will be classified as Adult-type diffuse astrocytoma, IDH mutant, grade 4 considering the recent tumor classification update." (PMID 35303162, 2022). "After histopathological and molecular analyses, the diagnosis of IDH1 (R132C)–mutated diffuse astrocytoma (grade II WHO) was established." (PMID 36284581, 2022). "IDH1 mutation and ATRX loss: Among seven patients with diffuse astrocytomas who had testing for IDH1 mutations performed on paired surgical specimens, two (29%) patients tested positive at diagnosis and remained positive at recurrence." (PMID 33153497, 2020). "IDH1 wild-type diffuse astrocytoma most frequently harbor BRAF p.V600E mutations, accounting for ~40% of cases." (PMID 32164789, 2020). "Low WT1 scores in grade II and III diffuse astrocytomas were linked to the high frequency of IDH1 positivity, and were associated with low Bcl2 and Ki67 labelling indices." (PMID 32856872, 2020). "We performed IHC analyses of IDH mutation using anti-IDH1 R132H antibody in those samples from patients with low-grade diffuse astrocytoma or with high-grade GBM, respectively." (PMID 30824700, 2019). "Mutations in IDH1/2 are a defining feature of diffuse astrocytomas and are almost always found in conjunction with inactivating mutations in ATRX and TP5314–17." (PMID 30087349, 2018). "In the HGG group, IDH1 R132H mutation was found in three patients with Grade 4 diffuse astrocytoma." (PMID 39684714, 2024). "Similarly, diffuse astrocytoma has a far better prognosis if there is a mutation in IDH1/2: 12.6 vs. 5.5 years." (PMID 27379174, 2016). "The presence of isocitrate dehydrogenase 1 (IDH1) and 2 (IDH2) mutations has been observed in diffuse astrocytomas (WHO grade II) and anaplastic astrocytomas (WHO grade III)." (PMID 41466163, 2025). "Age distribution of IDH1/2 wt diffuse astrocytomas have been reported to vary among different WHO grades." (PMID 38326661, 2024). "A stereotactic biopsy of the left frontal lesion, performed at another institution, was in favor of a WHO grade II IDH-1 (R132-H) mutant fibrillary diffuse astrocytoma, with proliferation index Ki67-MIB1 1%." (PMID 35884525, 2022). "The tumor was diagnosed post-surgery as a grade II diffuse astrocytoma, IDH1-wild type, ATRX-deleted." (PMID 33222010, 2021).
diffuse astrocytoma (continued). "In contrast, gene mutations for IDH1 and IDH2 were found with high frequency in diffuse astrocytomas (70–80 %) and anaplastic astrocytomas (up to 50 %)." (PMID 27379174, 2016). "Therefore, our remit was to assess the influence of treatment regimens by analyzing the clinical course of a large cohort of IDH1/2 wt diffuse astrocytoma patients from six neurosurgical sites treated in the 2016–2019 period." (PMID 38326661, 2024). "In contrast to diffuse astrocytomas, IDH1 mutation status does not serve as a prognostic factor since PAs have been consistently described as IDH1 wildtype tumors." (PMID 31362435, 2019). "Patients with IDH1-mut diffuse astrocytomas lived significantly longer." (PMID 30857299, 2019). "Symptomatic tumor progression was suspected in 2018, leading to a surgical tumor biopsy that demonstrated WHO grade 4 IDH1 and IDH2 mutant diffuse astrocytoma." (PMID 37077830, 2023). "Nuclear ATRX expression was retained, and IDH1 R132H immunostaining was negative, suggesting diagnosis of a pilocytic astrocytoma and arguing against an isocitrate dehydrogenase (IDH)-mutant diffuse astrocytoma." (PMID 41458616, 2025). "These alterations have also been described in the adult age group where they represented ~50% of so-called isomorphic diffuse glioma (a subtype of IDH1 wild-type, BRAF p.V600E negative diffuse astrocytoma) in both children and adults." (PMID 32164789, 2020).